TLR3 (toll like receptor 3)
Diseases named in the same sentence as TLR3 in open-access papers (continued):
Sharing a sentence is not in itself a finding about the gene and the disease.
influenza (continued). "To further explore the nature of the inflammatory response to viruses and TLR3 agonists in Peli1−/− animals, we examined the cells recruited to the airways in response to influenza infection over 8 days by flow cytometry." (PMID 32984077, 2020). "When TLR3 knockout mice were infected with influenza they had a surprising survival advantage over wildtype mice, despite having higher viral titres in their lungs, highlighting the complex role of this PRR in influenza restriction." (PMID 32477965, 2020). "Unexpectedly, one of these variants has been reported in patients with life-threatening influenza pneumonia (TLR3 p.Pro554Ser) and another was shown to be both deleterious and dominant-negative (IFNAR1 p.Pro335del)." (PMID 32972995, 2020). "In the case of influenza, TLR3 and RIG-I recognize either double or single stranded RNA and both have been implicated in optimizing the host cellular response to influenza." (PMID 31416461, 2019). "We here sought to study the role of TLR3-signaling during pandemic influenza infection by either adding a TLR3 agonist, or inhibiting the response by ssON." (PMID 31572376, 2019). "In the case of influenza, it is the TLR3 that acts as an early warning system for the infected epithelial cells." (PMID 31416461, 2019). "Here we demonstrate both in vivo and in vitro that IL-22Ra1 is induced rapidly after influenza infection in a TLR3 dependent manner." (PMID 31416461, 2019). "This is borne out by animal studies which indicate that, despite an elevated viral load, tlr3−/− mice show decreased infiltration of inflammatory cells into the lungs and increased survival rates following lethal influenza challenge." (PMID 29552008, 2018). "Treatments that activate TLR3 in mice have been reported to enhance antiviral immunity, including induction of protection against influenza." (PMID 22299046, 2012). "Deletion of TLR3 leads to downregulation of inflammatory cytokine and chemokine production and an elevated viral load during the late phase of influenza infection." (PMID 21108806, 2010). "TLR3 agonists have been used previously as safe adjuvants for intranasal immunization of human volunteers with trivalent influenza vaccine or as monotherapy post-exposure prophylaxis given up to 48 h post challenge with influenza or rhinovirus." (PMID 36944687, 2023). "The first breakthrough emerged from a study testing the hypothesis that candidate inborn errors of TLR3-, IRF7-, and IRF9-dependent type I IFN immunity previously shown to underlie life-threatening influenza pneumonia might also underlie critical COVID-19." (PMID 37196358, 2023). "Mice deficient for TLR3 or its adapter molecule, toll/interleukin-1 receptor (TIR)-domain-containing adapter-inducing interferon-β (TRIF), demonstrate normal humoral and T-cell responses to sublethal influenza infection." (PMID 32962304, 2020). "TLR3 recognition of influenza is part of the epithelial cells immediate response to infection." (PMID 31416461, 2019). "However, influenza infection stimulated a similar increase in the frequency and total number of lung MCp in both Tlr3−/− and wild type mice." (PMID 30337928, 2018). "In mice, influenza infection is sensed by toll-like receptor 3 (TLR3), TLR7, retinoid acid-inducible gene I (RIG-I), melanoma differentiation associated protein 5 (MDA-5), and the NOD-like receptor family member NOD-, LRR- and pyrin domain-containing 3 (NLRP3)." (PMID 30337928, 2018). "Next, we investigated whether TLR3 is involved in the influenza-induced recruitment of MCp to the lung." (PMID 30337928, 2018). "Only double knockdown of RIG-I and TLR3 completely inhibited IFN induction by influenza." (PMID 30532653, 2018). "The increased IFN-α after influenza infection could be related to the upregulation of TLR3 mRNA in CLEC5A−/− mice, as observed after PIC treatment." (PMID 27795434, 2017).
influenza (continued). "For instance, stimulation of other pattern recognition receptors that respond to influenza, such as TLR3, TLR7, and RIG-I, could affect pneumococcal transmission, as shown for TLR2." (PMID 25166617, 2014). "The inhibited virus-specific TLR3/7 correlated with reduced influenza replication (M gene) in mice treated with etanercept, which indicated that blocking TNF-α enhanced host control of virus replication, but the elucidation of a possible mechanism requires more experimental investigation." (PMID 24373231, 2013). "The aim of this study was to evaluate whether selected polymorphisms of TLR2, TLR3 and TLR4 influence the incidence and clinical picture of pandemic A/H1N1/2009 influenza." (PMID 23151015, 2012). "We tested whether treatment of mice with the TLR3 agonist poly(I∶C) would protect against influenza in our lethal infection model." (PMID 22299046, 2012). "The role of TLR3 in the immune response to influenza has been debated in the literature." (PMID 21108806, 2010). "The finding that TLR3 is upregulated in human bronchial and alveolar epithelial cells during influenza infection suggests that it may play an important role in immune signaling." (PMID 21108806, 2010). "The adjuvant effect of TLR3 agonist on the generation of S-specific CD8+ T cells within the lungs is in agreement with previous reports indicating that TLR3 agonists can improve the efficacy of live smallpox vaccines, inactivated influenza vaccines, and live influenza vaccine." (PMID 37854858, 2023). "However, it has been shown that TLR7/8 potentiates rather than activates oxylipin synthesis, notably on subsequent stimulation by fMLP, platelet-activating factor, and the ionophore A2318734 suggesting that in our influenza stimulation model, only TLR3/MDA5 has been engaged in the oxylipin response." (PMID 37575177, 2023). "Loss-of-function mutations in Toll-like receptor 3 (TLR3) and interferon regulatory factor 7 (IRF7), which are also important in influenza infections, can lead to increased vulnerability to SARS-CoV-2 infections and might explain severe cases in young and otherwise healthy individuals." (PMID 33804918, 2021). "Thus, TLR3 might be dispensable for the induction of the adaptive immune response following IAV infection, although TLR3 agonists serve as important adjuvants for influenza vaccines." (PMID 32962304, 2020). "We first tested the specific hypothesis that inborn errors of Toll-like receptor 3 (TLR3)– and interferon regulatory factor 7 (IRF7)–dependent type I interferon (IFN) immunity, which underlie life-threatening influenza pneumonia, may also underlie life-threatening COVID-19 pneumonia." (PMID 32972995, 2020). "We tested the specific hypothesis that inborn errors of Toll-like receptor 3 (TLR3)– and interferon regulatory factor 7 (IRF7)–dependent type I interferon (IFN) immunity that underlie life-threatening influenza pneumonia also underlie life-threatening COVID-19 pneumonia." (PMID 32972995, 2020). "However, TLR3 signaling does not seem important for adaptive immune responses against influenza, because T and B cell responses are unaffected by TLR3 deficiency." (PMID 32375274, 2020). "It has been shown that TLR3 and TLR7 make the main contribution to innate defences against influenza viruses, but there are few published data concerning the importance of polymorphisms of these and other TLRs in conditioning susceptibility to influenza or the severity of the disease." (PMID 23151015, 2012). "TLR3, TLR7, TLR9, and RIG1 are known to be involved in sensing influenza viral antigens and activating downstream signaling pathways." (PMID 39846844, 2025). "Our first breakthrough was the discovery of inborn errors in TLR3-dependent type I IFN production and response in patients with hypoxemic COVID-19 pneumonia, which showed that critical COVID-19 and influenza pneumonia can indeed be allelic." (PMID 41347066, 2025).
influenza (continued). "The TLR3 agonist PolyI:C showed strong mucosal adjuvant activity for the H1N1, H3N2, and H5N1 split influenza vaccine." (PMID 39597683, 2024). "TLR3, TLR7, TLR8, and RIG-I are known to be involved in sensing influenza viral Ags and activating downstream signaling pathways." (PMID 38112660, 2023). "The interaction between the TLR4 and adjuvant enhance the immune response, while TLR3, TLR4 and TLR9 agonists have been used to improve vaccines against HBV, influenza, malaria and anthrax." (PMID 35371033, 2022). "PRRs sensing viral RNAs, such as RIG-I, TLR3 and TLR7, have emerged as critical intracellular receptors for the innate immunity against influenza infection." (PMID 35503798, 2022). "In influenza inoculated BMMCs, signaling through double-stranded RNA-sensing PRRs RIG-I and TLR3 strongly induces IL-6 and the proinflammatory leukotriene LTB4." (PMID 33680987, 2021). "Although virus recognition by TLR initiates many intrinsic antiviral defenses, TLR stimulation can enhance disease severity, as exemplified by TLR3 and TLR4-mediated detrimental inflammatory responses during influenza and WNV infection." (PMID 34696494, 2021). "Inborn errors in TLR3-mediated immune response can explain at least severe HSV1 and influenza complications in some patients." (PMID 32936395, 2020). "Ducks utilize many of the same PRRs to detect influenza, namely RIG-I, TLR7, and TLR3 and their downstream adaptors." (PMID 32477965, 2020). "Changes in expression of different toll-like receptors (TLRs) (TLR2, TLR3, TLR4, TLR7, TLR8, and TLR9) have been reported before in human monocytes and dendritic cells from seasonal influenza infected patients." (PMID 30682165, 2019). "Host innate immunity mediates the first line of defense towards influenza infection and TLR-7 and TLR-3 are the main sensors for influenza viruses, responsible for triggering the host’s innate immune responses in chickens." (PMID 30823888, 2019). "Influenza infections are recognized by TLRs, such as TLR7 that binds ssRNA and TLR3, which senses dsRNA in the endosomes." (PMID 31572376, 2019). "A significant role of TLR3- and ST2-signaling in the immune response against influenza infection was demonstrated before." (PMID 30337928, 2018). "Altogether, our data indicate that TLR3- and ST2-mediated signals are dispensable for influenza-induced recruitment of MCp to the lung, and that other receptors are involved in this process." (PMID 30337928, 2018). "In contrast, the influenza-induced recruitment of mast cell progenitors to the lung occurred independently of either TLR3 or ST2, as demonstrated using Tlr3−/− or Il1rl1−/− mice." (PMID 30337928, 2018). "However, in the present study both Tlr3- and Il1rl1-deficient mice had an intact recruitment of MCp to the lung in response to the influenza infection and blocking the IL-33/ST2 pathway in Tlr3−/− mice could not either abrogate the influx." (PMID 30337928, 2018). "The comparison of the KEGG “Influenza” response pathway led to the identification of nodes targeted by C. burnetii and B. abortus to down-modulate TLR4/TLR3, STAT1 and type I IFN-responsive genes." (PMID 24915541, 2014). "In particular, TLR3, TLR4 and TLR9 agonists have been shown to improve a number of vaccines, for example against HBV, influenza, malaria and anthrax, as well as some types of cancer." (PMID 26344622, 2014). "Additionally, using poly I:C (TLR3) and Pam3CSK4 (TLR1/2) adjuvant combination for influenza and anthrax vaccine enhanced antibody production by B-cell in vivo." (PMID 40277916, 2025). "Another recent study demonstrates that intranasal vaccination with a commercial influenza vaccine adjuvanted with NexaVant (NVT), a TLR3 agonist, effectively boosts lung CD4+ TRM cells, which are key to cross-protective, long-lasting immunity against diverse influenza strains." (PMID 40407543, 2025). "TFPI correlated negatively with TLR3 and TLR7 in COVID19 but positively in influenza." (PMID 40825056, 2025).
influenza (continued). "TLRs, such as TLR3, TLR7, and TLR8, are membrane-bound PRRs that recognize viral RNA: TLR3 detects double-stranded RNA (dsRNA), a byproduct of influenza replication, TLR7/8 sense single-stranded RNA (ssRNA) from the viral genome, while TLR2 and TLR4 recognize influenza-induced DAMPs." (PMID 40692679, 2025). "Although IAV does not produce dsRNA during replication, TLR3 activation can occur during influenza infection." (PMID 32375274, 2020). "The negative impact of TLR3 activation during influenza was revealed using TLR3−/− mice, which survived longer than wild-type mice following lethal influenza infection despite sustained high viral load in the lungs." (PMID 31572376, 2019). "We previously demonstrated that a TLR3 agonist alone induced a protective immune response and, in combination with a TLR7 agonist, achieved immediate and complete protection against lethal influenza infection." (PMID 29445364, 2018). "We demonstrated that HBEC from smokers have a diminished RIG-I and TLR3-initiated antiviral response to influenza infection compared to nonsmokers." (PMID 27604339, 2016). "RIG-I and TLR3-initiated antiviral responses in infected human lung epithelial cells are well known for their ability to reduce viral replication, and both type I and type III IFNs inhibit influenza replication." (PMID 27604339, 2016). "These cases revealed the indispensable role of human intrinsic (TLR3, IRF7, IRF9, STAT1, and STAT2 in RECs, in which the virus replicates) and innate (IRF7 in plasmacytoid dendritic cells, in which the virus does not replicate) type I and III IFN immunity in host defense against influenza." (PMID 36112363, 2022). "However, influenza infection of Tlr3-/- or IL-33 receptor Il1rl1-/- mice showed no reduction in MC progenitor recruitment." (PMID 33680987, 2021). "Interestingly, RIG-I and MDA-5 increased to a higher change than TLR3 and TLR7 at 6 hpi, suggesting RLRs might play more vital roles in sensing RNA at early stage of influenza infection than TLRs." (PMID 26008703, 2015). "The TLR3 rs5743313/CT polymorphism was found in all of the children with pneumonia and influenza infection, but in a significantly smaller number of those with A/H1N1/2009 influenza without pneumonia (<0.0001)." (PMID 23151015, 2012). "Although these results may seem counter-intuitive, the activation of the TLR3- or the IL-33/ST2 pathways alone triggered only a few-fold increase in lung MCp, which is by far not as impressive as the massive recruitment of MCp to the lung induced by influenza infection." (PMID 30337928, 2018). "Furthermore, neutralization of IL-33 in Tlr3−/− mice could not abrogate the influenza-induced influx of mast cell progenitors to the lung." (PMID 30337928, 2018). "Although several studies have shown that dsRNA is not produced during influenza replication, very low and potentially undetectable levels of this viral intermediate could still elicit a substantial immune response through TLR3." (PMID 21108806, 2010). "It has not yet been demonstrated whether influenza H5N1 affects TLR3/TLR9 signalling pathways." (PMID 19325820, 2008). "It was shown that TLR3, TLR7 and MyD88 signaling is not required for efficient T responses during influenza infection, but both TLR7 and MyD88 are critical for B cell responses during influenza infection." (PMID 25539593, 2014). "However, absence of either TLR3 or ST2 alone, or blocking IL-33 in Tlr3−/− mice did not influence the massive influenza-induced recruitment of MCp to the lung, implicating that other pathways are involved in this process." (PMID 30337928, 2018). "Interestingly, MCp accumulate in the lung also in response to weaker innate stimulation such as upon i.n. injections of ligands to TLR3 and ST2, although not to the same level as the live influenza infection." (PMID 30337928, 2018).
influenza (continued). "Poly (ICLC), a dsRNA, and CpG ODNs, molecular mimics for TLR3 and TLR9, respectively, have been reported to non-specifically stimulate the innate immune system and to provide protection against various bacterial and viral pathogens, including influenza." (PMID 19325820, 2008). "While IL24 expression has been shown following PM exposure and demonstrates antiviral activity, neither PM nor influenza alone induced IL24 at either 2 or 24 hours, suggesting potentially elevated antiviral activity through IL-24-mediated priming through mechanisms such as TLR3-mediated apoptosis." (PMID 40671793, 2025).